RBM22 (RNA binding motif protein 22)
Description:
Required for pre-mRNA splicing as component of the activated spliceosome. Involved in the first step of pre-mRNA splicing. Binds directly to the internal stem-loop (ISL) domain of the U6 snRNA and to the pre-mRNA intron near the 5' splice site during the activation and catalytic phases of the spliceosome cycle. Involved in both translocations of the nuclear SLU7 to the cytoplasm and the cytosolic calcium-binding protein PDCD6 to the nucleus upon cellular stress responses.
Synonyms: ZC3H16; FLJ10290; fSAP47; Cwc2
Tractability: Small molecule: a structure with a bound ligand is known. PROTAC: UniProt records ubiquitination sites on it; ubiquitination databases record sites on it; its protein half-life has been measured.
Gene: Protein-coding gene on chromosome 5 (150,690,792 to 150,701,077, reverse strand). Ensembl gene ENSG00000086589.
Subcellular location: Nucleus; Cytoplasm
Subcellular location (Human Protein Atlas): Nucleoplasm
Pathways (Reactome):
Disease: Dengue Virus-Host Interactions
Metabolism of RNA: mRNA Splicing - Major Pathway
Gene Ontology:
Molecular function: calcium-dependent protein binding; pre-mRNA binding; protein binding; RNA binding; U6 snRNA binding; metal ion binding; nucleic acid binding
Biological process: cellular response to xenobiotic stimulus; mRNA cis splicing, via spliceosome; positive regulation of protein export from nucleus; positive regulation of protein import into nucleus; positive regulation of RNA splicing; mRNA splicing, via spliceosome
Cellular component: catalytic step 2 spliceosome; cytoplasm; nucleoplasm; nucleus; post-mRNA release spliceosomal complex; post-spliceosomal complex; spliceosomal complex; U2-type catalytic step 1 spliceosome; U2-type catalytic step 2 spliceosome; Prp19 complex
Genetic constraint (gnomAD): Loss-of-function variants: 1 observed, 51.56 expected, observed/expected ratio (o/e) 0.0194, 90% interval 0.006 to 0.092. The upper end of that interval is the gene's LOEUF score, 0.092, which puts it in group 1 of 6, group 1 being the genes least tolerant of losing a copy. Missense variants: 264 observed, 547.53 expected, observed/expected ratio (o/e) 0.48, 90% interval 0.44 to 0.53. Synonymous variants: 152 observed, 187.26 expected, observed/expected ratio (o/e) 0.81, 90% interval 0.71 to 0.93.
Homologues: Orthologues: dog RBM22 (100% identical), guinea pig RBM22 (100% identical), macaque RBM22 (100% identical), mouse Rbm22 (100% identical), rabbit RBM22 (100% identical), rat Rbm22 (99% identical), pig RBM22 (99% identical), chimpanzee RBM22 (97% identical), tropical clawed frog rbm22 (89% identical), zebrafish rbm22 (86% identical), Drosophila melanogaster CG14641 (59% identical), Caenorhabditis elegans rbm-22 (52% identical).
Diseases named in the same sentence as RBM22 in open-access papers:
RBM22 is named in the same sentence as 13 diseases in open-access papers, as found by Europe PMC text mining. Sharing a sentence is not in itself a finding about the gene and the disease. The quoted sentences say what the papers report.
breast carcinoma (1 paper, 2025). "Recent studies demonstrated that RBM22 depletion affects cell viability and proliferation of glioblastoma and breast cancer cells." (PMID 40142004, 2025).
colon cancer (1 paper, 2025). "However, the role of RBM22 in colon cancer and the molecular mechanisms underlying its tumor-suppressive function remain largely unclear." (PMID 40142004, 2025). "However, the anti-cancer effects and underlying molecular mechanisms of RBM22 in colon cancer remain unclear." (PMID 40142004, 2025). "Silencing RBM22 results in a significant reduction in c-Myc expression, accompanied by increased apoptosis and decreased viability of colon cancer cells." (PMID 40142004, 2025). "In summary, our findings reveal that RBM22 functions as a tumor suppressor in colon cancer by regulating the c-Myc stability, a key factor in cancer cell proliferation and survival." (PMID 40142004, 2025). "In this study, we demonstrate that RBM22 induces apoptosis and suppresses colon cancer cell viability and proliferation by modulating c-Myc expression." (PMID 40142004, 2025). "Our study demonstrates the potential of RBM22 as a therapeutic target for modulating c-Myc-driven oncogenesis in colon cancer." (PMID 40142004, 2025). "Therefore, RBM22 is expected to be used for treatment as a direct target in colon cancer, and research on related inhibitors is needed." (PMID 40142004, 2025). "We confirmed RBM22 expression and demonstrated its overexpression in colon cancer cells." (PMID 40142004, 2025).
colorectal cancer (1 paper, 2021). A primary or metastatic malignant neoplasm that affects the colon or rectum. "Interestingly, cleaved PARP was augmented by the downregulation of RBM22 and U2AF1, suggesting that RBM22 and U2AF1 inhibited apoptosis and promoted the tumor progression in colorectal cancer cells through cyclin B1 and/or cyclin D1-dissociated mechanisms." (PMID 34202873, 2021).
glioblastoma (1 paper, 2025). The most malignant astrocytic tumor (WHO grade IV). "According to several studies, RBM22 was identified as a crucial factor for cancer cells and is overexpressed in triple-negative breast cancer and glioblastoma cells." (PMID 40142004, 2025).
glioma (1 paper, 2022). A benign or malignant brain and spinal cord tumor that arises from glial cells (astrocytes, oligodendrocytes, ependymal cells). "Moreover, Sf3b1 expression was also significantly correlated with key glioma/spliceosome -markers (Mki67/Pdgfra/Rbm22/Sf3b1)." (PMID 35086552, 2022).
myelodysplastic syndrome (1 paper, 2022). A clonal hematopoietic disorder characterized by dysplasia and ineffective hematopoiesis in one or more of the hematopoietic cell lines. "Undoubtedly due to its wide scope in the regulation of gene expression, RBM22 has been associated with several pathologies and, notably, with the aggressiveness of cancer cells and with the phenotype of a myelodysplastic syndrome." (PMID 35158909, 2022). "In 2007, RBM22 was identified as one of the most downregulated genes in the 5q-syndrome, a subtype of myelodysplastic syndrome." (PMID 35158909, 2022).
pancreatic cancer (1 paper, 2021). "Western blotting showed that cleaved PARP was increased by the downregulation of RBM22 in HCT116 and SUIT-2 cells but not OE33 cells, suggesting that RBM22 inhibited apoptosis, thereby promoting the progression of colorectal and pancreatic cancer." (PMID 34202873, 2021).
cancer (5 papers, 2019 to 2025). A tumor composed of atypical neoplastic, often pleomorphic cells that invade other tissues. "Therefore, our findings suggest that RBM22 depletion regulates cancer cell proliferation and induces apoptosis via the c-Myc pathway." (PMID 40142004, 2025). "However, further research, including in vivo studies, is required to elucidate the anti-cancer mechanisms of RBM22 in CRC." (PMID 40142004, 2025). "The OGEE v3 database describes RBM22 as essential for cancer cells in several human tissues." (PMID 35158909, 2022). "Future investigations of RBM22 will undoubtedly provide new insights in the coupling of gene transcription and RNA processing, as well as a better understanding of pathological situations, notably in cancer." (PMID 35158909, 2022). "Consequently, RBM22 alterations are observed in several diseases and notably in cancer." (PMID 35158909, 2022). "RBM22 could represent a potential therapeutic target in specific diseases, and, notably, in cancer." (PMID 35158909, 2022). "Four riboSNitch-depleted 5′UTRs (ING3, RBM22, NSA2 and TAF2) were detected at the q-value cutoff of 0.05, and all of these elements were cancer-specific." (PMID 31160636, 2019). "Altogether, these data suggest that even though RBM22 does not appear to be a driver gene in cancers and other diseases, it seems that it plays an important role in survival, mitosis and differentiation processes, and participates in pathological states." (PMID 35158909, 2022). "DHX8, EIF3G, RBM22, U2AF1 UPF1 and YBX-1 are also candidates therapeutic targets for cancer therapy because the tumor cell progression was strongly inhibited by the downregulation of these RBPs in cancer cells, including HCT116, SUIT2 and OE33 cells, but not in non-cancerous cells." (PMID 34202873, 2021). "Additionally, the apoptosis inhibitor Z-VAD-FMK, but not the autophagy inhibitor 3-MA, rescued cancer cell viability, demonstrating that RBM22 is involved in apoptosis rather than autophagy." (PMID 40142004, 2025).
tumor (4 papers, 2021 to 2025). "Our study revealed that RBM22 is involved in apoptosis and proliferation and is emerging as a novel regulator of other tumor-related genes." (PMID 40142004, 2025). "Consequently, our findings suggest that RBM22 functions as a tumor suppressor by regulating cell survival and proliferation and inducing apoptosis via c-Myc." (PMID 40142004, 2025). "Indeed, being deregulated in several diseases, RBM22 was repeatedly described to play an oncogenic cooperation role with implications in cell proliferation, migration, and tumor aggressiveness." (PMID 35158909, 2022). "RBM22 modulates c-Myc through CNOT2 and MID1IP1, influencing c-Myc stability and contributing to a shortened half-life, thereby revealing its tumor-suppressive functions." (PMID 40142004, 2025). "A robust correlation between SF3B1 expression and the most critical oncogenic spliceosome components [SRSF3/RBM22/PTPB1/RBM3] was also found in GBM (CGGA- and Rembrandt-datasets), but not in the non-tumor samples (with the exception of PTBP1; Rembrandt-datasets)." (PMID 35086552, 2022). "Interestingly, the induction of cleaved PARP was not strongly induced by the downregulation of RBM22 and U2AF1, suggesting that some RBPs promoted tumor progression via a tissue-specific mechanisms." (PMID 34202873, 2021).
hematological malignancies (1 paper, 2022). "Finally, in accordance with the higher expression of RBM22 in hematopoietic tissues mentioned earlier, RBM22 alterations are also reported in hematological malignancies." (PMID 35158909, 2022).
RBM22 also shares sentences with these, for which no sentence is quoted: esophageal cancer (1 paper); myeloid leukemia (1); PRLomas (1).